GSDMC (gasdermin C)
Diseases named in the same sentence as GSDMC in open-access papers (continued):
Sharing a sentence is not in itself a finding about the gene and the disease.
tumor (124 papers, 2016 to 2026). "Together, these results suggest a possible association between GSDMC expression and the immunosuppressive tumor microenvironment in PDAC." (PMID 39297408, 2024). "GSDMC-fueled PARPi efficacy in both BRCA-proficient and -deficient tumors in multiple cancer types, but BRCA deficiency reduced more tumor growth in GSDMC-positive tumors." (PMID 37883181, 2024). "GSDMC was first discovered as a tumor‐associated gene in 2004, which is closely associated with melanoma metastasis." (PMID 37125240, 2023). "This research illustrated that ncRNAs-mediated upregulation of GSDMC was linked to dismal prognosis and also exhibited a correlation with tumor immune cell infiltration in BRCA." (PMID 36042287, 2022). "This study illustrated that ncRNAs-mediated upregulation of GSDMC linked to dismal prognosis and also exhibited a correlation with tumor immune cell infiltration in BRCA." (PMID 36042287, 2022). "The metabolite α-KG induces death receptor 6-activated caspase-8 which activates the GSDMC-dependent pyroptosis pathway in cancer cells, causing tumor necrosis." (PMID 36042287, 2022). "The CM risk factor, GSDMC, was negatively associated with RNAss, indicating that GSDMC promotes the proliferation of tumor cells and inhibits the differentiation of tumor stem cells through different pathways." (PMID 34721986, 2021). "In addition, we investigated the potential correlation between the expression of PLAU/GSDMC and tumor-associated immune cells." (PMID 41584044, 2026). "In this study, we confirmed that GSDMC expression shows a decrease in the keratinocytes of OLP and the downregulation of GSDMC in oral keratinocytes results in cell apoptosis, consistent with other studies noting that GSDMC knockout is associated with apoptosis in tumor cell." (PMID 37741915, 2023). "GSDMC also suppresses gastric cell proliferation but upregulation is observed in certain cancers such as melanoma, colorectal and lung adenocarcinoma which is associated with tumor growth and metastasis." (PMID 36605187, 2022). "All these outcomes illustrated that tumor immune evasion and antitumor immunity might be implicated in GSDMC mediated carcinogenic processes of BRCA." (PMID 36042287, 2022). "In addition, GSDMC expression was associated with an immune-hot tumor microenvironment." (PMID 41584044, 2026). "In tumor microenvironment, the tumor-associated macrophages could secret the TNFα, and induce tumor necrosis through the activation of caspase-8, the translocation of PD-L1, and the cleavage of GSDMC." (PMID 34421915, 2021). "The PARPi treatment can enhance GSDMC mediated pyroptosis and GSDMC can sensitize tumor cells to PARPi via an immune-dependent manner, which forms a positive feedback loop to achieve a better treatment response." (PMID 40064873, 2025). "This DdBIC antitumor effect was dependent on Nur77- and GSDMC-mediated pyroptosis, as the knockdown of either Nur77 or GSDMC in A375 cells mitigated the suppression of tumor growth." (PMID 41407678, 2025). "Tumour cells with increased expression of gasdermin C (GSDMC) predicted better treatment response to PARPi in TNBC through the activation of GSDMC/caspase-8–mediated cancer cell pyroptosis (CCP) enhancing tumour microenvironment cytotoxicity." (PMID 40192976, 2025). "Intraperitoneal injection of DdBIC significantly reduced xenograft tumor growth in a dose-dependent manner, with GSDMC and OPA1 cleavage and eIF2α phosphorylation." (PMID 41407678, 2025). "High GSDMC expression was observed in 95% (21/22) of grade 3 CRC cases and 68% (34/50) of grade 1/2 CRC cases, suggesting a potential positive correlation between GSDMC expression levels and tumor progression." (PMID 40213993, 2025). "The roles of Nur77/GSDMC-mediated pyroptosis in tumor growth were further investigated in mouse models." (PMID 41407678, 2025).
tumor (continued). "Irradiated wild‐type (WT) recipients reconstituted with WT or Gsdmc2–4−/− bone marrow cells showed comparable tumor size, tumor number, and tumor load, suggesting that GSDMC in immune cells is dispensable for AOM‐DSS induced CRC progression." (PMID 40213993, 2025). "Overexpression of GSDMC significantly promoted in vivo tumor cell proliferation, as indicated by the increased Ki67 staining signal, as well as the increased intensity of microvessels (CD31 staining) in both CT26 tumors and MC38 tumors." (PMID 40213993, 2025). "To study the role of GSDMC in tumor pathogenesis, we first assessed the expression of four GSDMC orthologs in mouse tissues and found abundant mRNA expression of GSDMC2, GSDMC3, and GSDMC4 in colon tissue; while, GSDMC1 mRNA expression was relatively low." (PMID 40213993, 2025). "Subsequent treatment with TNF-α results in caspase-8-mediated cleavage of GSDMC, leading to pyroptosis and tumor necrosis in breast cancer." (PMID 39300122, 2024). "Targeting GSDMC genetically or pharmacologically in murine models reduces tumor growth and metastasis, partly by reprogramming the immunosuppressive tumor microenvironment." (PMID 39297408, 2024). "PARPi triggers pyroptosis, not apoptosis, which is a “clean death” that inhibits immune response, in GSDMC-positive tumor cells, providing a new perspective for PARPi treatment that cell death pattern is another important consideration beyond BRCA mutation." (PMID 37883181, 2024). "Immunohistochemistry of tumor specimens shows enhanced GSDMC protein expression for invading vimentin+ PDAC cells in vivo and ex vivo spheroids." (PMID 39297408, 2024). "Certain antibiotic chemotherapy agents have been observed to elevate the levels of nPD-L1 and GSDMC while inducing caspase-8, leading to pyroptosis within tumor cells." (PMID 38304430, 2024). "This study demonstrated for the first time that nuclear PD-L1, caspase-8, and GSDMC are essential for macrophage-derived TNFα-induced tumor necrosis." (PMID 38877579, 2024). "Macrophage‐secreted TNF‐α binds to TNFR on the surface of tumour cells and induces caspase‐8 cleavage of GSDMC, reversing the apoptotic pathway into pyroptosis and contributing to anti‐tumour immunity." (PMID 38652105, 2024). "GSDMC is highly expressed in the gastrointestinal tract and also participates in anti-tumor immunity; however, its role as a tumor suppressor or promoter remains uncertain, potentially related to the duration and intensity of the inflammatory response." (PMID 39595526, 2024). "In contrast to the significant suppression of tumor growth in vitro, GSDMC-mediated CCP slightly suppressed tumor growth in response to PARPi treatment in nude mice." (PMID 37883181, 2024). "Under hypoxia, the formation of nPD-L1/p-Stat3 complex increases the expression of GSDMC in different cancer cells, converting apoptosis to pyroptosis so as to promote tumor progression and suppress anti-tumor immune responses." (PMID 38654314, 2024). "Here, we show that GSDMC expression increases PARPi sensitivity through CCP-induced memory T cell expansion in the tumor microenvironment and in lymphoid organs, which enhances antitumor immunity in multiple cancer types." (PMID 37883181, 2024). "Macrophage TNF-α-driven tumor cell pyroptotic death requires nuclear PD-L1, caspase-8, and GSDMC in vivo." (PMID 39300122, 2024). "GSDMC-mediated CCP suppressed tumor growth by increasing tumor infiltration and activation of cytotoxic and memory T cells." (PMID 37883181, 2024). "To investigate the mechanism of GSDMC-mediated antitumor immunity, we analyzed the tumor-infiltrating immune cells under PARPi treatment." (PMID 37883181, 2024). "PARPi treatment triggered GSDMC/caspase-8–mediated cancer cell pyroptosis (CCP) that enhanced PARPi killing of tumor cells." (PMID 37883181, 2024). "GSDMC is activated in acidic or tumor microenvironments, triggering pyroptosis through pore formation to help limit tumor spread." (PMID 39735183, 2024).
tumor (continued). "Here, we show that gasdermin C (GSDMC) sensitized tumor cells to PARPi in vitro and in immunocompetent mice and caused durable tumor regression in an immune-dependent manner." (PMID 37883181, 2024). "Hypoxic properties in TME catalyse the binding of PD‐L1 and p‐STAT3 in the nucleus of tumour cells, leading to nuclear translocation and increasing GSDMC expression." (PMID 38652105, 2024). "In TNBC, about 38.5% of cancer patients’ tumor tissues show high expression of GSDMC, indicating that PARPi has potential in TNBC treatment." (PMID 39273650, 2024). "Meanwhile, PD-L1 was suggested to in turn regulate gasdermin C expression and switch apoptosis to pyroptosis in cancer cells and further to facilitate tumor necrosis." (PMID 37863886, 2023). "Our results indicated that, except for NLRP6 and GSDMC, the expressions of most PRGs were higher in tumor tissues compared to normal tissues." (PMID 37214439, 2023). "A recent study revealed that upon TNF-α treatment, the active caspase-8 cleaves GSDMC, which unleashes the pore-forming GSDMC-NT to trigger pyroptosis in tumor cells." (PMID 36742298, 2023). "Univariate and multivariate regression analyses showed that CASP8, GSDMC, age, and new tumor type were independent factors influencing the prognosis of patients with PAAD." (PMID 36882663, 2023). "The results of an interesting study indicate that PD-L1 mediates the atypical pyroptosis in cancer cells through GSDMC/caspase-8, leading to tumor necrosis." (PMID 37061535, 2023). "It was proposed that GSDMC-mediated CAP promotes tumor progression by generating necrosis in tumors." (PMID 36742298, 2023). "As mentioned, α-KG has shown its ability to trigger GSDMC-mediated pyroptosis and suppress tumor growth." (PMID 36742298, 2023). "Hypoxia‐induced formation of the PD‐L1/STAT3 complex promotes expression of GSDMC to induce pyroptosis, followed by tumor necrosis in hypoxic regions, which suppress antitumor immune response from pyroptosis and is critical to tumor proliferation." (PMID 36161280, 2023). "NLRP6 and GSDME showed elevated methylation levels in tumor samples, while GSDMC showed the opposite characteristics." (PMID 35651286, 2023). "We then constructed a nomogram for clinical prediction based on CASP3, CASP5, CASP8, GSDMC, age, and tumor status." (PMID 36882663, 2023). "Activated caspase-8 cleaves GSDMC at D365, leading to the release of its N-terminal domain, which transforms cell apoptosis into tumor focal death." (PMID 35883480, 2022). "First, via the TCGA dataset, we examined the levels of mRNA expression of GSDMC in 10,363 tumor tissues and 730 adjoining tissues from 18 kinds of cancer." (PMID 36042287, 2022). "For another important aspect of this research, our research demonstrated that GSDMC was a pivotal player in BC carcinogenesis via elevating tumor immune cell infiltration and the expression of immunological checkpoints." (PMID 36042287, 2022). "In our study, GSDMC seemed to be a oncogene, since it was expressed nearly twice as strongly in tumor tissues as in normal tissues, contributing to a decrease in patient survival." (PMID 35677632, 2022). "Subsequently, IHC was performed to validate the expression of GSDMC in 15 pairs of BC tumor tissues and corresponding adjacent normal tissues." (PMID 36042287, 2022). "According to recent literature, the phosphorylated signal transducer and activator of transcription 3 (STAT3) and programmed cell death receptor ligand 1 (PDL1) complex can promote the expression of GSDMC in tumor cells." (PMID 35883480, 2022). "Previous studies confirmed that over-expression of GSDMC enhanced cell proliferation and xenograft tumor growth." (PMID 35922531, 2022). "Statistical analysis revealed that GSDMC was also expressed significantly highly in BC tissues than in the adjacent non-tumor tissues (P < 0.001)." (PMID 36042287, 2022). "In BRCA, GSDMC had a specifically solid function in tumor purity and the infiltration of myeloid dendritic cells, neutrophils." (PMID 36042287, 2022).
tumor (continued). "When the correlation analysis of gasdermin family gene expression with tumor microenvironment was performed in PAAD, we found that all members except for GSDMC showed a significant association with RNAss." (PMID 35922531, 2022). "In 2016, it was shown that silencing GSDMC in CRC lines promotes tumor growth in vivo and in vitro, supporting the anti-tumor role of pyroptosis in CRC and uncovering GSDMC as a new oncogene." (PMID 36077828, 2022). "In order to validate these, we further assessed how GSDMC expression differs in pan tumor types in TCGA databases via Tumor Immune Estimation Resource (TIMER)." (PMID 36042287, 2022). "Recent studies have shown that the immune checkpoint molecule PD-L1 can switch the apoptosis of tumor cells to pyroptosis by mediating the expression of GSDMC." (PMID 36186792, 2022). "Our results indicate that the expression of GSDMC decreased as the tumor grade increased and is a factor that indicates favorable prognosis." (PMID 35784306, 2022). "One study found that PD-L1 mediated expression of GSDMC converts apoptosis of cancer cells to pyroptosis and promotes tumor necrosis." (PMID 35228524, 2022). "They demonstrated that tumor hypoxia induced PD-L1 nuclear translocation, accompanied by activation of GSDMC expression and pyroptosis induction." (PMID 36936274, 2022). "IHC analysis of 15 pairs of BC tumor tissues and corresponding adjacent normal tissues also revealed significantly higher expression of GSDMC in BC tissues than normal tissues." (PMID 36042287, 2022). "GSDMC is regulated by transforming growth factor-beta (TGF-β) signaling and is associated with tumor cell proliferation." (PMID 36003332, 2022). "Macrophage-derived TNF-α-induced tumor pyroptosis requires nuclear PD-L1, caspase-8, and GSDMC In vivo." (PMID 33776057, 2021). "Administration of DM-αKG evidently suppressed tumor growth in a DR6- and GSDMC-dependent manner and was associated with DM-αKG-induced GSDMC cleavage." (PMID 34012073, 2021). "GSDMC has been reported to be upregulated by transforming growth factor beta receptor 2 (TGFBR2) mutation in colorectal cancer (CRC), promoting tumor cell proliferation." (PMID 34298833, 2021). "GSDMC is specifically cleaved by caspase-8 at Asp240 and is related to tumor progression in breast cancer due to the induction of chronic inflammation." (PMID 34522213, 2021). "This GSDMC-dependent inflammasome signaling and pyroptosis pathway will significantly change the tumor microenvironment, promote tumor progression and increase the resistance to chemotherapy, radiotherapy and immunotherapy." (PMID 34421915, 2021). "GSDMC was related to a variety of tumor biological behaviors, but many biological functions were currently controversial." (PMID 34778452, 2021). "Elevated levels of GSDMC result in a switch from TNFα-induced apoptosis to pyroptosis and eventually tumor necrosis." (PMID 34522213, 2021). "Upon administration of DM-αKG, DR6-dependent cleavage of GSDMC in xenograft tumor tissues was clearly observed." (PMID 34012073, 2021). "DR6-mediated and GSDMC-executed pyroptosis was required for this inhibitory effect of α-KG, as knockdown of either DR6 or GSDMC in HeLa cells almost abolished the suppressive effect of DM-αKG on tumor growth." (PMID 34012073, 2021). "Further experiments confirmed that GSDMC promoted tumor cell proliferation in colorectal carcinogenesis." (PMID 27835699, 2016). "The tumor growth speed in mice inoculated with GSDMC-knockdown cells was significantly slower than that in the control group." (PMID 27835699, 2016). "In addition, the median expression levels of GSDMC were significantly higher in tumor tissues for most of the cancers analyzed (13/17)." (PMID 40213993, 2025). "On the other hand, T cell-derived granzyme B activates caspase-6 to cleave GSDMC, implying that combining PARPi with immune checkpoint inhibitors could synergistically amplify tumor clearance." (PMID 41291696, 2025).
tumor (continued). "Fourth, DdBIC-induced pyroptosis was associated with GSDMC cleavage in various cancer cell lines, and knockdown of GSDMC suppressed DdBIC-induced pyroptosis in three tumor cell lines, further suggesting that DdBIC acts as a broad-spectrum inducer of GSDMC-mediated pyroptosis." (PMID 41407678, 2025). "To further investigate the effect of Caspase‐6‐mediated GSDMC activation on tumor development, we intraperitoneally injected vehicle or 5mg kg−1 Caspase‐6 inhibitor Z‐VEID‐FMK every other day for 30 days, starting at day 40 of the AOM‐DSS induced CRC mouse model." (PMID 40213993, 2025). "Deletion of GSDMC or caspase-8 significantly decreased sensitivity of tumor cells to PARPi." (PMID 37883181, 2024). "GSDMC-increased efficacy of PARPi was observed in BRCA-deficient and BRCA-proficient cells, indicating that BRCA deficiency is not absolutely required for, but seems to strengthen, the effects for GSDMC-sensitizing tumor cells to PARPi." (PMID 37883181, 2024). "Another study discovered that the metabolite α-ketoglutarate (α-KG) could induce pyroptosis via caspase-8-mediated GSDMC cleavage, inhibiting tumor growth and metastasis in a mouse model." (PMID 39062587, 2024). "However, tumor growth eventually progresses despite GSDMC inhibition, as differentiated PDAC cells continue to proliferate and immune surveillance wanes." (PMID 39297408, 2024). "The expression of GSDMC was significantly and negatively correlated with the tumor purity of LIHC (p < 0.05), while it was significantly and positively correlated with the degree of infiltration of B cells, CD4+ T cells, macrophages, neutrophils and dendritic cells." (PMID 38434972, 2024). "Considering the late observations that cancer cell pyroptosis (CCP), as a form of ICD, suppressed tumor growth by activating antitumor immunity, we asked whether the CCP-induced antitumor immunity by GSDMC might sensitize tumor cells to PARPi treatment." (PMID 37883181, 2024). "In addition, in vivo experiments show that inhibiting GSDMC transcription and thereby suppressing pyroptosis alleviates tumor necrosis symptoms and prolongs the survival of tumor-bearing mice." (PMID 38229080, 2024). "This research not only elucidates a pyroptotic pathway associated with metabolites but also unveils a previously unreported central pathway extending from ROS-triggered DR6 endocytosis to caspase-8-mediated cleavage of GSDMC, suggesting potential clinical applications in tumor therapy." (PMID 38877579, 2024). "GSDMC/caspase-8 mediates a non-canonical pyroptosis pathway in cancer cells, causing tumor necrosis." (PMID 39723212, 2024). "GSDMC also inhibits cell growth and decreases tumor proliferation in gastric and esophageal cancer." (PMID 39062587, 2024). "The study raises a possibility that GSDMC may sensitize tumor cells to these DDR inhibitors as it does to PARPi." (PMID 37883181, 2024). "Theoretically, GSDMC can sensitize tumor cells to the treatment of any drugs that could activate caspase-6 or caspase-8, or could stimulate antitumor immunity response." (PMID 37883181, 2024). "α-Ketoglutarate (α-KG), an essential metabolite in the tricarboxylic acid (TCA) cycle, could also induce GSDMC-mediated pyroptosis in tumor cells." (PMID 36742298, 2023). "Intriguingly however, there are mixed observations on the role of GSDMC in tumour biology." (PMID 37266429, 2023). "Notably, pyroptosis induced by GSDMC in hypoxic regions promotes tumor development and suppresses the antitumor immune response." (PMID 38066523, 2023). "There is also evidence that the intravenous delivery of an immunotherapy based on Listeria monocytogenes encapsulated in red blood cell membrane was able to drive GSDMC-mediated pyroptosis in the tumour, successfully dampening the suppressive environment of the tumour." (PMID 37266429, 2023). "However, several studies had revealed that the expression profile and biological function of GSDMC in different tumor tissues are inconsistent." (PMID 36823153, 2023).